CCL2 (C-C motif chemokine ligand 2)
Diseases named in the same sentence as CCL2 in open-access papers (continued):
Sharing a sentence is not in itself a finding about the gene and the disease.
Cirrhosis (45 papers, 2007 to 2025). A chronic disorder of the liver in which liver tissue becomes scarred and is partially replaced by regenerative nodules and fibrotic tissue resulting in loss of liver function. "We could demonstrate that hepatic transcription of CCL2 correlates with disease severity and cirrhosis-associated complications." (PMID 32218781, 2020). "Therefore, we speculate that the decrease in CCL2 observed in our patients with end-stage ALD may be due to cirrhosis-related fat loss, and that this reduction might be less pronounced in GG carriers due to impaired lipid metabolism." (PMID 40731922, 2025). "Chemokine CCL2, a multifunctional factor implicated in various aspects of liver pathogenesis such as acute liver injury, chronic HBV/HCV infection, cirrhosis, and tumorigenesis, is regarded as a reliable indicator of potential signal sources in SLE." (PMID 37312878, 2023). "There is evidence also for a spleen-liver crosstalk, given a study showed reduced fibrosis, monocyte infiltration within the injured liver and CCL2 secretion by hepatic macrophages in cirrhosis patients that had undergone splenectomy." (PMID 36926073, 2022). "Plasma IL6 and CCL2 were significantly increased in the bariatric population compared to lean controls, while high levels were detected in patients with cirrhosis which is in keeping with previous publications from our group." (PMID 27992443, 2016). "Supporting our hypothesis that PDE4D promotes inflammatory cell infiltration, CCL2 levels in the livers of patients with cirrhosis were significantly increased compared with healthy individuals and correlated with PDE4D levels." (PMID 41196648, 2025). "In chronic HBV cases complicated by cirrhosis, plasma CCL2 levels tend to decrease." (PMID 39850880, 2024). "In a prospective clinical analysis, human patients with HCC but not cirrhosis had increased plasma levels of CCL2 and IL13 that was associated with invasive and multifocal disease." (PMID 31933479, 2020). "Increased levels of C-C motif chemokine ligand 2 (CCL2), interleukin (IL)-18, IL-33, and citrullinated histone H3 (CitH3)—an accurate marker of neutrophil extracellular traps (NETs)—were detected in the circulation of patients with acute infection or early cirrhosis." (PMID 40565198, 2025). "We could observe that hepatic macrophages are possibly the main source of elevated systemic MCP-1 in decompensated cirrhosis, shown by increased hepatic transcription of CCL2 in correlation with the number of hepatic macrophages (F4/80 staining) and increased MCP-1 levels in hepatic vein blood." (PMID 32218781, 2020). "Monocyte chemoattractant protein-1 (CCL2/MCP-1), a strong chemotactic factor for histiocytes, shows increased expression in various fibrotic disorders like hepatic cirrhosis, nephrosclerosis, and progressive systemic sclerosis." (PMID 41226448, 2025). "We observed that C-C motif chemokine ligand 2 (CCL2), interleukin (IL)-18, and interleukin (IL)-33 were elevated in the circulation of patients with either acute infection (a-HBV) or early cirrhosis (cir-HBV), in contrast to healthy individuals (HI)." (PMID 40565198, 2025). "Prior to the presence of cirrhosis, in ARLD and NAFLD, hepatic macrophages become activated by LPS, IFN-ɣ, and GM-CSF signalling and show pro-inflammatory cytokine/chemokine secretion (IL-6, IL-1β, and CCL2)." (PMID 36926073, 2022). "Finally, in the plasma of patients with HCC (n = 25) but not cirrhosis (n = 10), CCL2 and IL13 were increased and IL13 predicted invasive tumors." (PMID 31933479, 2020). "Therefore, we speculate that the upregulated expression of QPCT also enhances the modification of the N-terminus of CCl2 and leads to improved activity of CCl2 in CHB patients with cirrhosis and liver cancer, which promotes CHB progression and the development of liver cirrhosis and liver cancer." (PMID 39531472, 2024). "Both CCL2 (p=0.006) and IL13 (p<0.0001), were significantly elevated in the plasma of patients with HCC but not cirrhosis." (PMID 31933479, 2020).
Cirrhosis (continued). "Upon detailed assessment, cytokine levels and cirrhosis etiology revealed that HBV-cirrhosis—regardless of antiviral therapy—had a 3-fold increase in IFN-γ, TRAIL and CXCL1 (GRO-α) levels and up to 3-fold decrease in MMP-2, CXCL12, IL2RA, IL-6Rα, CCL2 (MCP1) and CCL21 (6kine) levels." (PMID 36230823, 2022).
experimental autoimmune encephalomyelitis (43 papers, 2007 to 2024). An autoimmune demyelinating disease of the central nervous system that is produced experimentally in animals by the injection of homogenized brain or spinal cord in Freund's adjuvant. "Increased CCL2 in MasR-deficient mice upon inflammatory stimulation or in the context of experimental autoimmune encephalomyelitis (EAE) was shown to promote the recruitment of inflammatory macrophages." (PMID 34874920, 2022). "CXCL10 and CCL2 play a role in attracting T cells and monocytes, respectively, and have been strongly implicated in disease in experimental autoimmune encephalomyelitis (EAE), an animal for MS." (PMID 31636637, 2019). "MSC-derived antagonistic CCL2 variant also inhibited inflammatory Th17 cell functions in experimental autoimmune encephalomyelitis model." (PMID 28117437, 2017). "In a rodent model of experimental autoimmune encephalomyelitis, deletion of the CCL2 gene resulted in a decrease in macrophage and T-cell infiltration, thus ameliorating disease severity in its late stages." (PMID 37765263, 2023). "CCL2 has been widely studied in the context of MS and its animal model—experimental autoimmune encephalomyelitis (EAE)." (PMID 37108633, 2023). "Models of experimental autoimmune encephalomyelitis (EAE) provided evidence that pro-inflammatory chemokines such as CCL2 produced mostly by astrocytes are involved in the pathogenesis of EAE and recruit T cells." (PMID 35443752, 2022). "Bindarit was further effective in attenuating clinical experimental autoimmune encephalomyelitis in mice by suppressing the elevation of CCL2 in the brain and spinal cord." (PMID 36611891, 2022). "Lif KO animals have increased expression of CXCL1, GM-CSF, RANTES/CCL5 and MIP-1β/CCL3 early during an experimental autoimmune encephalomyelitis model and reduced CCL2, CCL3, and CXCL10 at a later stage of the disease." (PMID 25277705, 2014). "CCL2 has been found to be up-regulated in actively demyelinating MS plaques, and its expression is increased in experimental autoimmune encephalomyelitis." (PMID 22524232, 2012). "Deficiencies in monocyte recruitment have also been reported after Ccl2 inhibition in other models such as skin inflammation, thioglycollate challenge, experimental autoimmune encephalomyelitis, pulmonary granuloma, and peripheral endotoxin insult." (PMID 22992301, 2012). "Moreover, the upregulation of Ccl2, Ccl3, Ccl4, Ccl7, Cxcl9, and Cxcl10 is also related to the acute phase of experimental autoimmune encephalomyelitis." (PMID 35911717, 2022). "MCP-1/CCL2, IL-8 and MIP-1α/CCL3 have been demonstrated to be important pro-inflammatory mediators involved in the pathogenesis of experimental autoimmune encephalomyelitis (EAE) and MS." (PMID 35309326, 2022). "In experimental autoimmune encephalomyelitis (EAE), activated M1 microglia upregulated CCL-2, which facilitated the recruitment of circulating monocytes to the injured sites, as well as TNF and iNOS, which contributed to inflammation." (PMID 36558562, 2022). "It has been reported in experimental autoimmune encephalomyelitis that mononuclear cell infiltration in the acute disease and the relapse phase is controlled by CCL3 or CCL2, respectively, suggesting a distinct functional differentiation of both chemokines." (PMID 26640428, 2015). "Mice devoid of CCR2 show a marked reduction in monocyte extravasation whereas mice lacking CCL2 show attenuated demyelination during experimental autoimmune encephalomyelitis." (PMID 37893243, 2023). "In contrast, mice lacking CCL2 exhibit decreased severity of experimental autoimmune encephalomyelitis with diminished Th1 cytokine secretion in the CNS." (PMID 23866683, 2013). "CXCL10/IP-10, CCL2/MCP-1, CCL3/MIP-1a, CCL4/MIP-1b, CCL5/Rantes, CCL7/MCP-3 and CXCL9/Mig are among the described proinflammatory chemokines produced by immune cells and CNS glia in MS and in the animal model of MS, experimental autoimmune encephalomyelitis (EAE)." (PMID 26039252, 2015).
experimental autoimmune encephalomyelitis (continued). "Previous studies showed MSCs inhibited experimental autoimmune encephalomyelitis- (EAE-) derived CD4+ T cell activation by suppressing STAT3 phosphorylation via CCL2, and CCL2−/− MSCs could not ameliorate disease and decrease Th17 cells in EAE mice." (PMID 25918734, 2015).
encephalitis (42 papers, 2010 to 2025). An acute inflammatory process affecting the brain parenchyma. "Meanwhile, miRNA-206 plays a critical role in many diseases, such as CCL2 as a direct target of miR-206, and the upregulation of CCL2 caused by the downregulation of miR-206 was responsible for the development of severe HEV71 encephalitis." (PMID 34900997, 2021). "Downregulation of CCL2 induced by the upregulation of microRNA206 is associated with the severity of HEV71 encephalitis." (PMID 34525985, 2021). "The CNS susceptibility to WNV-mediated encephalitis can also be a function of the up-regulation of CCL2 response we observe in both BafA1- and Rapa-treated U-251 cells." (PMID 32225060, 2020). "Following CHPV infection expression levels of TNF-a, CCL2 and IL-6 were found to increase that was previously implicated in playing decisive roles in encephalitis has decreased significantly after (-)-25b treatment." (PMID 30001342, 2018). "CCL-2 was reported to mediate the accumulation of inflammatory monocytes in the brain, and their differentiation into microglia decreased survival, thus playing a pathogenic role in encephalitis caused by WNV." (PMID 39339151, 2024). "Importantly, the upregulation of CCL2 was associated with the severity of encephalitis in EV-A71-infected patients." (PMID 35110649, 2022). "Ccl2 which is also known as monocyte chemoattractant protein-1 (MCP-1) has also been implicated in encephalitis caused by viruses including VEEV, and has been shown to play role in permeability of blood brain barrier and leukocyte migration into the brain parenchyma." (PMID 28446152, 2017). "We also monitored Ccl2 mRNA, as this cytokine has also been associated with RVFV encephalitis and was differentially expressed in our RNAseq experiments." (PMID 38935789, 2024). "Three studies with 201 encephalitis patients and 66 controls investigated the CSF concentration of CCL2." (PMID 36048783, 2022). "According to an experimental acute viral encephalitis model of CCL2(-/-) knockout mice, CCL2 is the key chemotactic factor that facilitates monocyte migration through glia limitans from the perivascular space." (PMID 35464431, 2022). "In vesicular stomatitis virus (VSV)-induced encephalitis model, administration of compound 21 increased C-C motif chemokine ligand 2 (CCL2) mRNA expression and decreased mice survival, which is associated with neuroprotective effects and lifetime." (PMID 32506972, 2020). "IL-4 CCL11, CCL17, CCL21), Th17 (IL-17A, GM-CSF), B cell molecules (BAFF, APRIL) and other cytokine/chemokines including IL-21, IL-1b, IL-12p40, CCL2 and IL-12p70 were detected in less than 50% of patients with encephalitis." (PMID 27575749, 2016). "The CCR2/CCL2 axis is pivotal for leukocyte trafficking, particularly monocytes, in the context of viral encephalitis." (PMID 27930721, 2016). "This is especially disappointing since CSF CCL2 has been used as a biomarker in SIV encephalitis, and was shown to be reduced by minocycline treatment in the SIV model." (PMID 21569420, 2011). "Moreover, in FIRES Th1-associated cytokines and chemokines, as well as IL-6, CCL2, CCL19, and CXCL1, resulted elevated when compared to the levels observed in encephalitis, which involved a broader network of cytokines/chemokines." (PMID 38078329, 2023). "The production of CCL2 by neurons during acute encephalitis may play a role in more than just leukocyte recruitment." (PMID 29202854, 2017). "While the relevance of our current findings to the neuropathological and electrophysiological sequelae of TMEV encephalitis remains to be determined, our observations lend further support to the therapeutic relevance of targeting the CCL2:CCR2 axis to confer neuroprotection." (PMID 29202854, 2017). "The elevated levels of IL-10, IL-6, IL-8, TNFα (cytokines) and CCL2 and CXCL9 (chemokines) in monocytes may help in predicting the pathogenicity of CHPV causing encephalitis and possible entry into the central nervous system." (PMID 27628855, 2016).
encephalitis (continued). "In line with a previous study of viral encephalitis we found higher relative levels of CCL-2 and IL-6 in the CSF than serum and higher levels of CCL-5 in serum; in our study this was also found in those with immune-mediated and unknown aetiologies." (PMID 26808276, 2016). "In contrast, CCL2 was increased in pigtail macaques that develop encephalitis." (PMID 23997430, 2013). "Significantly higher levels of CCL11 (p = 0.0107), CCL2 (p = 0.0182), CCL5 (p = 0.0171) and CXCL5 (p = 0.0049) were observed in encephalitis patients." (PMID 40517242, 2025). "Significant methylation alterations were found in the promoters of CSF3, CCL2, and ICAM1 in LGI1 encephalitis patients comparable to healthy individuals." (PMID 37644514, 2023). "In the context of viral encephalitis, alteration or blockade of the CCR2/CCL2 axis can significantly reduce the infiltration of inflammatory monocytes into the infected brain." (PMID 27930721, 2016). "CCL2 mRNA was upregulated in cultured astrocytes, but remained at low levels compared to CCL7, suggesting a role for CCL7 in HIV-related encephalitis." (PMID 23997430, 2013). "In addition, LGI1 encephalitis patients with brain MRI abnormalities presented the elevated level of PDL2 and CCL2 but lower levels of TNFα (all p < 0.05) in serum." (PMID 37644514, 2023). "The Clements group at Johns Hopkins has shown increased CCL2 mRNA in brain extracts using a highly accelerated encephalitis model, although mRNA does not always equate with secreted protein." (PMID 23997430, 2013). "We conclude that intracranial inoculation with infectious TMEV rapidly induces the expression of CCL2 in neurons, and this cellular source is necessary for CCR2-dependent infiltration of inflammatory monocytes into the brain during the most acute stage of encephalitis." (PMID 29202854, 2017). "Overall, we conclude that infection of the brain with TMEV rapidly induces CCL2 expression in neurons and this cellular source is central to driving CCR2-dependent infiltration of inflammatory monocytes into the brain during the most acute stage of encephalitis." (PMID 29202854, 2017). "Additionally, marked elevation of several immune markers (CCL11, CCL2, CCL5, CXCL5, and IL-12p70) in the CSF of encephalitis patients may explain the more severe course of infection and poorer outcomes observed (highest number of neurological symptoms and ICU admissions)." (PMID 40517242, 2025).
aneurysm (41 papers, 2013 to 2025). Bulging or ballooning in an area of an artery secondary to arterial wall weakening. "We chose to investigate this further given the importance of CCL2 release from VSMC in aneurysm and arteriosclerosis development." (PMID 32323032, 2020). "Local delivery of monocyte chemotactic protein-1 (MCP-1/CCL2) via our drug-eluting coil has been shown to promote intrasaccular aneurysm healing via an inflammatory pathway." (PMID 29615957, 2018). "Finally, there was also increased expression of pro-inflammatory endothelial chemokines (e.g., Ccl2, Il6), known to potentiate inflammatory processes and to be involved in aneurysm pathophysiology." (PMID 38965173, 2024). "In addition, we measured expression of potent mononuclear chemoattractants and found that chemokine CCL2 had significantly lower expression in aneurysms than in controls, while the chemokine CCL4 showed only a tendency to a lower expression in aneurysms." (PMID 26539497, 2015).